IL33 (interleukin 33)
Diseases named in the same sentence as IL33 in open-access papers (continued):
Sharing a sentence is not in itself a finding about the gene and the disease.
colitis (137 papers, 2011 to 2026). Inflammation of the colon. "IL-33-deficient mice were protected against carcinogen-induced skin cancer, suggesting that the IL-33-Treg axis contributes to chronic inflammation-driven tumorigenesis, including colitis-associated colorectal cancer." (PMID 41281748, 2025). "Our investigation corroborates earlier work showing that IL-33 facilitates the generation of IgA, contributing to the preservation of gut microbial homeostasis while mitigating IL-1α–induced colitis and colitis-associated cancer." (PMID 40048372, 2025). "One of the mechanisms by which antibiotics increase susceptibility to colitis is by decreasing the level of IL-33 in the colon." (PMID 38376154, 2024). "Amphiregulin has been reported to function downstream of the IL-33 pathway to repair epithelial damage caused by dextran sodium sulfate (DSS)-induced colitis." (PMID 38376154, 2024). "Studies have shown that both IL-33 deficiency and the administration of recombinant IL-33 ameliorated experimental colitis in mice." (PMID 38058517, 2023). "Bregs inhibited pathogenic Th17 cells in an IL-33 and PD-L1-dependent manner thereby suppressing colitis and subsequent CAC." (PMID 36263033, 2022). "In ulcerative colitis, blocking the IL-33 signaling pathway significantly reduced active disease; however, IL-33-deficient mice are highly susceptible to colitis and colorectal cancer." (PMID 36613465, 2022). "For instance, IL-33 promotes the macrophages autophagy in the setting of experimental colitis and IL-33 macrophagic activity is associated with the conversion of LC3-I to LC3-II." (PMID 36362246, 2022). "In agreement with this, IL-33 abundance was elevated in colon biopsies of IBD patients and IL-33 deficient mice were protected from DSS induced colitis while exogenous IL-33 aggravated disease." (PMID 36189323, 2022). "In the mouse model, treating with recombinant IL-33 cleared trophozoites from the mouse cecum and helped in early recovery from colitis, as evidence by decreased weight loss and epithelial damage." (PMID 34400793, 2022). "Cohousing IL-33-deficient and IL-33-replete mice before DSS treatment allowed equilibration of the gut microbiota and abrogated the increased colitis in IL-33-deficient mice seen upon DSS treatment." (PMID 36263033, 2022). "On the other hand, IL-33-deficient mice presented high susceptibility to colitis and colorectal cancer, potentially suggesting a protective role as a mediator of intestinal immunity." (PMID 36614065, 2022). "In acute experimental colitis, we observed loss of Spry2 rapidly during the injury phase, which correlated with increased IL-33 levels." (PMID 33547321, 2021). "On the one hand, IL-33 has been described to ameliorate intestinal inflammation in different mouse models of chemical induced colitis and to prevent Clostridium difficile associated colon pathology." (PMID 34335571, 2021). "Studies in other mice models indicated that IL‐33‐stimulated Bregs restore colon homeostasis and effectively block the development of spontaneous colitis in IL‐10‐deficient mice." (PMID 32566227, 2020). "The susceptibility of IL-33 deficient mice to colitis has been shown to be a result of the ability of IL-33 to promote IgA production from B cells, which notably plays a major role in maintaining microbial homeostasis in the intestine." (PMID 31139196, 2019). "In summary, these studies demonstrate that IL-33 signaling to ILC2s is an essential pathway for recovery from C. difficile-associated colitis." (PMID 31221971, 2019). "Consistent with our previous observation that treatment with IL-33 ameliorated the severity of colitis, improved the loss of animal body weight, relieved the activity of illness, and decreased the infiltration of inflammatory leukocytes." (PMID 30651971, 2019).
colitis (continued). "In contrast with these findings, IL-33-deficient mice have been shown to be highly susceptible to colitis and colorectal cancer, which would suggest a role as an important protective mediator of intestinal immunity." (PMID 31139196, 2019). "We found that severe colitis in aHPD-fed RAG2−/− mice is associated with high levels of homeostatic cytokine IL-33 and pro-inflammatory cytokines TNF-α and IL-6." (PMID 31105710, 2019). "In a subsequent study, the role of IL-1α as a driver of DSS-induced colitis in IL-33-deficient mice has also been established." (PMID 29766049, 2018). "IL-33 is also implicated in colitis in humans and in mouse models, suggesting a general role for IL-33 signaling in the mediation of host-microbe interactions at epithelial barrier surfaces." (PMID 29378633, 2018). "Further study to discover a pathway associated with goblet cell modulation by IL-33 during colitis is warranted." (PMID 28404987, 2017). "Conversely, IL-33 deficiency ameliorated dextran sodium sulfate-induced colitis and conferred resistance to lipopolysaccharide-induced endotoxinic shock in mice." (PMID 27317338, 2016). "Our present study shows that mice deficient in IL-25 are partially protected from DSS-induced colitis in mice associated with lower expression of IL-33 and other pro-inflammatory cytokines/mediators in the colon." (PMID 25937893, 2014). "In fact, data generated on the spontaneous enteritis characterizing SAMP mice suggests a frank pathogenic role, while IL-33 KO mice undergoing DSS colitis develop a mixed response." (PMID 23766561, 2013). "Upon genotype-phenotype evaluation, an increased frequency of extensive colitis in adult UC (P = 0.019) and in steroid-responsive pediatric patients (P = 0.024) carrying the IL-33 rs3939286 risk genotype, was observed." (PMID 23634226, 2013). "An increased frequency of extensive colitis (E3vsE1) was observed in UC adult patients carrying the IL-33 rs3939286 risk genotypes (AG+AA) (47% vs. 33%; P = 0.019) compared with those carrying the GG wild-type genotype." (PMID 23634226, 2013). "IL33-deficient mice are susceptible to DSS-induced colitis, similar to Rbbp9-/- mice." (PMID 39631567, 2025). "Studies suggest that IL-33 may have more of a protective role in experimental colitis; IL-33 deficient mice were found to be highly susceptible to colitis." (PMID 40642091, 2025). "The results of this study also showed that exogenous IL-33 causes exacerbation of colitis." (PMID 35410210, 2022). "(50, 100, 200 mg/kg) could protect against the TNBS-caused colitis in a rat model by decreasing the levels of IL-33, IL-5, IL-13, IL-6 cytokines and expression of IL-33 and ST2 proteins to inhibit the IL-33/ST2 signaling pathway." (PMID 36160392, 2022). "Moreover, IL-33 has been shown to act on B cells to promote the production of IgA, which, in turn, protects mice from colitis and colitis-associated cancer." (PMID 34400793, 2022). "Indeed, the protective and pathogenic functions of IL-37 during colitis were consistent with those of other members of the IL-1 family, including IL-1, IL-33, and IL-36 35-38." (PMID 35836813, 2022). "IL-33 might be one of pathogenic cytokines accounting for simultaneous occurrence of colitis and pancreatitis though further studies are required." (PMID 34759844, 2021). "Similar observations were seen in IL-33 deficient mice with DSS-induced colitis." (PMID 34581755, 2021). "We observed that deficiency of the IL-33 signaling pathway attenuates bacterial-induced colitis." (PMID 33654214, 2021). "It has been shown in IL-33−/− and IL-33+/+ mice that IL-33 deficiency leads to delayed local inflammation by reducing neutrophil chemoattractant factors, resulting in delayed resolution of tissue damage during dextrin sodium sulfate-induced colitis." (PMID 32151084, 2020).
colitis (continued). "In models of transplantable and colitis-associated colorectal cancer, tumor growth reduction induced by IL-33 was abrogated in eosinophil-deficient ΔdblGATA-1 mice, but was restored by adoptive transfer of eosinophils activated with IL-33 ex vivo." (PMID 33329534, 2020). "Others have reported that there are differences in the gut microbiomes of IL-33−/− versus WT mice and that cohousing WT and IL-33−/− mice reduces differences in their gut microbiomes and ablates IL-33-dependent differences in susceptibility to colitis in these mice." (PMID 31455422, 2019). "Whether IL-33 or related pathway is involved in RAI16 deficiency associated colitis or CAC still needs further study." (PMID 31862898, 2019). "Given its association with boosting type 2 immunity, IL-33 may act as a “balancing” cytokine in TNBS colitis." (PMID 31139196, 2019). "Additionally, IL-33-deficient mice have been reported to be highly associated with colitis and colitis-associated cancer, indicating that IL-33 has a protective effect in intestinal immunity." (PMID 31640262, 2019). "Supporting this, IL-33 deficient mice developed dysbiosis, characterized by increased levels of mucolytic and colitogenic bacteria, which drastically altered the microbial landscape of the gut making the mice more susceptible to colitis." (PMID 31139196, 2019). "Moreover, high levels of A. muciniphila were reported in IL-33-deficient mice and correlated with elevated expression of IL-1α, which was essential for induction of a severe form of colitis." (PMID 29766049, 2018). "In addition, the transfer of IL-33-induced, IL-10-producing regulatory B cells to IL-10-deficient mice reduced colitis severity and delayed disease onset." (PMID 29922293, 2018). "Thus, for example, IL-33-deficient mice with severe patterns of colitis showed improved disease parameters, including colon length, histology score, and weight loss, when cohoused with WT mice." (PMID 29766049, 2018). "suggests that IL-33 treatment could protect against the TNBS-induced colitis by enhancing Foxp3 expression associated with Treg functions." (PMID 24491821, 2014). "Furthermore, IL-33 exacerbates acute colitis in association with the induction of proinflammatory and angiogenic cytokine as well as chemokine production in a ST2 and IL-4 dependent manner." (PMID 25032216, 2014). "In addition, an increased frequency of extensive colitis in adults with UC and in steroid-responsive pediatric patients carrying the IL-33 risk polymorphism was observed." (PMID 24701033, 2014). "This likely reflects the context-dependent nature of these pathways; IL-33 appears to have important roles in resolution of inflammation and tissue repair, but is also associated with both pro-inflammatory and anti-inflammatory functions in colitis mouse models." (PMID 40972535, 2025). "In contrast to the chronic Il10-deficient model, we observed a sevenfold increase in colon Il33 expression in acute colitis induced by epithelial injury from DSS compared to untreated WT mice, indicating that factors specific to DSS colitis may be regulating IL-33." (PMID 33953267, 2021). "Although IL-33 is strongly implicated in inducing eosinophilic inflammation in anti-parasite or allergic type 2 immune responses, the cytokine has also shown protective effects in models of colitis, graft-vs.-host disease, autoimmunity, obesity, wound healing and tissue restoration." (PMID 32695116, 2020). "The IL-33 signaling pathway plays a crucial role in promoting the humoral immune response and protecting against infection and reinfection by C. difficile colitis via the action of ILC2s." (PMID 40048372, 2025). "A mouse model of DSS-induced colitis demonstrated that intestinal epithelial cells and fibroblasts locally produce IL-33, which promotes mucosal healing via the IL-33-ST2 axis." (PMID 39428941, 2025).
colitis (continued). "In the 2,4,6-trinitrobenzene sulfonic acid (TNBS) colitis model, some studies found that the administration of recombinant IL-33 ameliorated colitis symptoms, while others showed it attenuated colitis via a Treg driven response." (PMID 40642091, 2025). "iTcES treatment resulted in a significant reduction in TNF-α, IL-1β, IL-23, IL-17F, and IL-33 levels; all of these cytokines are known to exacerbate colitis by promoting intestinal epithelial cell death and disrupting the epithelial barrier." (PMID 40576745, 2025). "iTcES also reduced the production of IL-33, a cytokine that is overexpressed in colitis, suggesting reduced damage to colonic tissue." (PMID 40576745, 2025). "In contrast, DSS-induced colitis mice that received TcES exhibited significant decreases in the production of TNF-α, IL-1β, and IL-33, as well as Th17-associated cytokines such as IL-23 and IL-17F." (PMID 40576745, 2025). "It has been shown that administration of the GLP‐1 receptor agonist liraglutide to a mouse colitis model induced transcriptional upregulation of the genes Ccl20, Il33 and Muc5b in Brunner's glands, which alleviated colitis." (PMID 41146523, 2025). "In rodents, IL-33 treatment impaired epithelial barrier permeability in vitro and in vivo in an experimental model of colitis in mice." (PMID 38590952, 2024). "For example, RORγT+ Helios− Tregs, induced by gut microbes, respond to tissue damage-induced IL-33 and can restrict tissue damage and prevent tumorigenesis during colitis." (PMID 39000453, 2024). "IL33 acts as a tumor suppressor gene by inhibiting the development of colon cancer in sporadic and colitis animal models." (PMID 38609520, 2024). "Amphiregulin is known to contribute to intestinal epithelial regeneration, and IL-33 was shown to activate the amphiregulin-EGFR pathway to repair intestinal damage during DSS colitis." (PMID 38376154, 2024). "A study found that IL-33 promoted Th2 and Treg cell responses to ameliorate colitis induced by trinitrobenzene sulfonic acid (TNBS) in mice in a Foxp3-dependent form." (PMID 37153553, 2023). "An application of IFNγ in vivo potentiated also the effects of IL-33 under steady-state conditions and increased colonic A-Eos numbers to levels observed during colitis." (PMID 37635158, 2023). "Another important Th2 cytokine is IL-33, which is elevated in UC patients and in mouse models of colitis induced with trinitrobenzenesulfonic acid (TNBS) or DSS." (PMID 36769019, 2023). "Others have used an extended 7-14-day recovery period to evaluate the protective potentials of IL-33 against DSS-induced colitis in mice." (PMID 38066482, 2023). "GATA3+Helios+ Tregs seem to have a thymic origin and react to the alarmin IL-33 produced in response to tissue damage, reducing tissue injury in colitis." (PMID 36769019, 2023). "In vivo, treatment with IFNγ potentiated the effects of IL-33, increasing colonic A-Eos frequencies to the levels observed during colitis." (PMID 36509106, 2023). "This, in turn, protected mice from DSS-induced colitis, with the study also pointing out that external introduction of IL-33 worsened colitis." (PMID 38288125, 2023). "NFE2L3 deficiency leads to decreased expression of IL-33 in mast cells, activation of the RAB signaling pathway, and the inhibitory effect of Treg cells, all of which slow the progression of colitis and IBD-related colon cancer." (PMID 37686309, 2023). "Cumulatively, our data suggest that IL-33 promotes the accumulation of A-Eos during colitis, and that A-Eos limit pathogen incursions and prevent excessive tissue damage through their bactericidal and T-cell-regulatory activities." (PMID 36509106, 2023). "The protective role of IL-33 in IBD was also observed in the DSS-induced colitis mouse model (BALB/c)." (PMID 37686309, 2023). "Conversely, another research found that IL-33 offered protection against DSS-induced colitis by bolstering the proliferation of ILC2 and Treg cells." (PMID 38288125, 2023).
colitis (continued). "In fact, treatment with IL-33 exacerbates the disease severity at the onset of dextran sodium sulfate-induced colitis, whereas it ameliorates the disease during the recovery phases." (PMID 38058517, 2023). "For instance, in models of colitis, IL‐33 has been shown to promote autophagy occurrence in macrophages." (PMID 37904695, 2023). "Studies in mice suggest that Reg3γ is a downstream mediator of IL-33 and has a protective role in colitis by reducing inflammation and oxidative stress." (PMID 37524871, 2023). "On the other hand, studies have demonstrated that IL-33 signaling via AREG represents a dominant pathway for gut-associated group 2 innate lymphoid cells, whose activation promotes protection against colitis and colitis-associated cancer." (PMID 37014710, 2023). "IL-33 can indirectly alter the microbiota to protect against colitis through the promotion of IgA production." (PMID 37686309, 2023). "IL-33 promotes IgA production to maintain gut microbial homeostasis and restrain colitis and tumorigenesis." (PMID 37686309, 2023). "This is supported by a TNBS colitis model, in which administration of recombinant IL-33 resulted in reduced development of disease via the activation of M2-like macrophage polarization." (PMID 36614065, 2022). "IL-33 treatment alleviates colitis in mouse models of Crohn’s disease by altering Th1 cells toward Th2 and Treg cells." (PMID 36291105, 2022). "A recent study presented IL-33-mediated tissue protection in a DSS colitis model, which was facilitated by ILC2 expression, in parallel with a Treg-supporting role." (PMID 36614065, 2022). "IL-33 aids the restoration of goblet cell function following the characteristic depletion seen in gut inflammation in the DSS-induced murine colitis model, suggesting a protective role against colitis." (PMID 38566909, 2022). "Adoptive transfer of ILC2s was sufficient to restore the IL-33-mediated protection from amebic colitis in RAG2−/−γC−/− mice." (PMID 34400793, 2022). "ST2-dependent IL-33 signalling disrupts intestinal barrier integrity resulting in increased serum LPS and IL-6 induction consistent with enhanced colitis." (PMID 36263033, 2022). "This was of interest because a number of recent studies have revealed the role of IL-33-mediated protection from experimental and infection-induced colitis in mouse models." (PMID 34400793, 2022). "To determine if ILC2s acted downstream of IL-33 signaling during protection from amebic colitis, we adoptively transferred ILC2s into RAG2−/−γc−/− mice." (PMID 34400793, 2022). "In parallel, IL-33-mediated improvement in a TNBS colitis model has been presented, dependent on Foxp3 expression, through the stimulation of Th2 and Treg immunity." (PMID 36614065, 2022). "Even in the same tissue, protein function can be time and context dependant as is the case for IL33, being a tumor suppressor during initial stages of colitis and an oncogene at later stages of the disease." (PMID 35091681, 2022). "In a murine colitis models, IL‐33 was reported to ameliorate disease progression by increasing M2 macrophage polarization, or by promoting macrophage autophagy." (PMID 35593111, 2022). "Hitherto, in murine DSS colitis models, ILC2s activated by IL-33 were demonstrated to have a protective effect." (PMID 36430676, 2022). "We also confirmed that colonic ILC2s obtained from DSS-induced colitis mice showed significantly reduced IL-5 production only when stimulated with IL-25 and IL-33 alone or in combination." (PMID 36268010, 2022). "Treatment of Liraglutide in a T-cell driven adoptive transfer colitis mouse model upregulated expression of IL-33, mucin 5b, and CCL20 in murine Brunner’s glands and improved colitis." (PMID 36386134, 2022). "We end by suggesting the IL11/IL33 axis as a potential therapeutic target for fibro-inflammatory diseases such as colitis, systemic sclerosis and rheumatoid arthritis." (PMID 36012165, 2022).